MUS81 (MUS81 structure-specific endonuclease subunit)
Diseases named in the same sentence as MUS81 in open-access papers (continued):
Sharing a sentence is not in itself a finding about the gene and the disease.
breast carcinoma (7 papers, 2015 to 2024). "Moroever, single nucleotide polymorphisms in human MUS81 that reduce protein activity are a proposed breast cancer susceptibility factor." (PMID 26415217, 2015). "Although Mus81 is recently associated with the chemosensitivity in human malignancies such as colon cancer and breast cancer 16, 17, 18, its role in chemotherapy of HCC, a usually chemorefractory tumor 19, still remains unknown." (PMID 26714930, 2016). "As a critical endonuclease in DNA repair, Mus81 is traditionally regarded as a tumor suppressor, but recently correlated with the sensitivity of mitomycin C and 5‐fluorouracil in colon cancer and breast cancer cells." (PMID 26714930, 2016). "It was recently documented that Mus81 inhibition by siRNA could improve the sensitivity of 5‐FU in human breast cancer MCF‐7 and T47D cells." (PMID 26714930, 2016). "In addition, Mus81 inhibition by small interfering RNA (siRNA) also exhibited the ability to enhance the sensitivity of 5‐fluorouracil (5‐FU) in two breast carcinoma cell lines 17, further suggesting Mus81 as a candidate therapeutic target for chemosensitization." (PMID 26714930, 2016). "MUS81 silencing inactivated ATM/Chk2, thereby enhancing the sensitivity of breast cancer cell MCF-7 to cisplatin." (PMID 35910852, 2022). "MUS81 defects sensitize cells to various genotoxic chemicals, and it was recently shown that inhibition of MUS81 sensitizes HR-proficient cancer cells to the PARP1 inhibitor, olaparib, an agent commonly used to treat cancers with HR defects, such as BRCA1- and BRCA2-defective breast cancers." (PMID 36203968, 2022).
Fanconi anemia (7 papers, 2011 to 2025). Fanconi anemia (FA) is a hereditary DNA repair disorder characterized by progressive pancytopenia with bone marrow failure, variable congenital malformations and predisposition to develop hematological or solid tumors. "For example, targeting of genes known to play roles in DNA damage repair (DDR), including RAD54L, MUS81, and 16 proteins in the Fanconi Anemia pathway, strongly sensitized cells to camptothecin, which generates protein–DNA adducts." (PMID 39903505, 2025). "In the replication-dependent repair process, the Fanconi anemia pathway is activated, resulting in the ubiquitylation of FANCD2-I, followed by unhooking of one side of crosslinking DNA strands by several nucleases, such as ERCC1-XPF and MUS81." (PMID 28077981, 2017).
lymphoma (5 papers, 2013 to 2022). A malignant (clonal) proliferation of B- lymphocytes or T- lymphocytes which involves the lymph nodes, bone marrow and/or extranodal sites. "However, MUS81 deficiency, even MUS81 insufficiency, leads to a dramatic susceptibility to cancers, especially lymphomas in mice through the first year of life." (PMID 33791310, 2021).
ovarian carcinoma (5 papers, 2011 to 2023). A malignant neoplasm originating from the surface ovarian epithelium. "The inhibition of MUS81 expression by shRNA in human ovarian cancer cells (A2870 and SKOV3) induced a mild sensitization to olaparib (IC50: 4 vs. 7 μM for A2870, 6 vs. 9 μM for SKOV3) that was associated with an increase in the expression of MCM2." (PMID 36765954, 2023). "Findings in ovarian cancer revealed that MUS81 silencing enhanced the sensitivity of cancer cells to Olaparib." (PMID 35910852, 2022). "In recent years, some scholars have proven that the MUS81 gene expression was remarkably upregulated in ovarian cancer, which aroused our research interest." (PMID 35910852, 2022). "In future work, we will try to clarify the specific mechanism of MUS81 in ovarian cancer." (PMID 31803609, 2019). "Similarly, there was a trend of abnormal MUS81 expression in ovarian cancer according to TCGA." (PMID 31803609, 2019). "Following treatment with platelet releasate, SK-OV-3 cells also showed expression changes in genes involved in, anti-autophagy in endometrial and ovarian cancer [KIAA1324/EIG121], as well as transcriptional regulation [ACTL6A], cell cycle[MUS81], cytoskeletal [TPM4] and homeostatic [TPM4] processes." (PMID 22022533, 2011).
Bloom syndrome (3 papers, 2012 to 2022). Bloom syndrome (BSyn) is a rare chromosomal breakage syndrome characterized by a marked genetic instability associated with pre- and postnatal growth retardation, facial sun-sensitive telangiectatic erythema, increased susceptibility to infections, and predisposition to cancer. "Again, the combined depletion rather than single depletion of MUS81/GEN1 or SLX1/GEN1 in Bloom’s Syndrome (BS) patient cells can break the intact replication fork, leading to improper chromosome segregation and S-phase arrest." (PMID 36077130, 2022). "Furthermore, a recent study suggests that MUS81, SLX4 and GEN1 can compensate for lack of the BLM helicase in human cells by resolving HJs in somatic Bloom's syndrome cells." (PMID 22927825, 2012).
colorectal cancer (3 papers, 2016 to 2022). A primary or metastatic malignant neoplasm that affects the colon or rectum. "Colorectal cancer cells deficient in DNA damage repair proteins, EME1 and MUS81, were significantly more sensitive to both agents." (PMID 26867983, 2016).
hepatocellular carcinoma (3 papers, 2015 to 2025). A malignant tumor that arises from hepatocytes. "Reduced MUS81 expression has also been observed in human carcinomas including hepatocellular carcinoma and colon carcinoma, and this is associated with poor prognosis." (PMID 26415217, 2015). "This study therefore aims to investigate the effects of Mus81 knockdown on the chemosensitivity of hepatocellular carcinoma (HCC), a usually chemorefractory tumor, and explore the underlying mechanisms." (PMID 26714930, 2016).
sarcoma (3 papers, 2015 to 2024). A usually aggressive malignant neoplasm of the soft tissue or bone.
colon carcinoma (2 papers, 2015 to 2016). "CHK1 and CHK2 were proved to be essential for cell cycle arrest before mitosis in response to DNA damage 22, and these two kinases was all activated by Mus81 deficiency in HCT116 colon cancer cells." (PMID 26714930, 2016).
liver cancer (2 papers, 2022). An epithelial or non-epithelial malignant neoplasm that arises from the liver. "A previous study showed that MUS81 knockdown reverses the G2-M block caused by epirubicin in liver cancer cells." (PMID 35480096, 2022).
Serous Ovarian Cancer (2 papers, 2019 to 2021). "In this study, we aim to elucidate the potential association between the dysfunction of MUS81 and the progression of Serous Ovarian Cancer (SOC)." (PMID 31803609, 2019). "The downregulation of MUS81 enhanced the sensitivity to camptothecin and olaparib in serous ovarian cancer cell lines and xenograft model, and also played a role as a potential marker for the malignancy of gastric cancer." (PMID 34527278, 2021). "The lack of MUS81 could improve the sensitivity of cisplatin as well as terminate the enlargement and intension of serous ovarian cancer." (PMID 34527278, 2021).
viral infection (2 papers, 2014 to 2015). "These experiments were performed using either of 2 independent shRNAs, and the extent of depletion of MUS81 was >90% in these cells within 48–72 hours of virus infection." (PMID 26415217, 2015). "We quantified replication fork progression in MUS81-depleted U2OS cells taken for analysis in the early stages of viral infection (3 days) before any signs of cellular senescence were evident." (PMID 26415217, 2015). "However, this is not the case, MUS81 depletion does not mimic a G2 arrest phenotype and MUS81 or SLX4 depletion reduces viral infection, which indicates their positive role for the viral life cycle." (PMID 25496524, 2014).
anemia (1 paper, 2013). A reduction in the number of red blood cells, the amount of hemoglobin, and/or the volume of packed red blood cells. "Hef is an archaeal member of the DNA repair endonuclease XPF (XPF)/Crossover junction endonuclease MUS81 (MUS81)/Fanconi anemia, complementation group M (FANCM) protein family that in eukaryotes participates in the restart of stalled DNA replication forks." (PMID 24049073, 2013).
Autoimmunity (1 paper, 2018). The occurrence of an immune reaction against the organism's own cells or tissues. "The presence of nucleic acids in the cytosol represents a danger signal activating the cytosolic surveillance system but cells develop strategies to avoid an excessive immune response leading to autoimmunity: endo- and exonucleases such as MUS81, ERCC1-XPF, DNaseII, and TREX155–58." (PMID 30523277, 2018).
cardiomyopathy (1 paper, 2024). A disease of the heart muscle or myocardium proper. "We analyzed the novel gene pair EYA4 and MUS81, where EYA4, involved in transcription, eye development, and DNA repair, is linked to hearing loss and cardiomyopathy, while MUS81 is essential for DNA repair." (PMID 39372928, 2024).
glioblastoma (1 paper, 2020). The most malignant astrocytic tumor (WHO grade IV). "Consistent with our results in MUS81 protein expression, our functional assays revealed that MUS81 p.R431H is significantly more rapidly degraded than its wild-type counterpart in thyroid and glioblastoma cell models." (PMID 32443704, 2020).
HIV-1 infection (1 paper, 2020). The type species of lentivirus and the etiologic agent of acquired immunodeficiency syndrome (AIDS). "Furthermore, our data suggest a potential link between IFNβ, decreased TGFβ signaling (SMAD4), increased unfolded protein response (VIMP and SEP15) and increased DNA damage (NUP54 and MUS81) in chronic HIV-1 infection." (PMID 33064743, 2020).
lentivirus infection (1 paper, 2016). Virus diseases caused by the Lentivirus genus. "Seventy‐two hours after lentivirus infection, the inhibition rate of Mus81 protein was measured by western blot." (PMID 26714930, 2016).
lung carcinoma (1 paper, 2016). "Although Mus81 expression has also been correlated with the chemosensitivity of other human malignancies such as lung cancer 18, the role of Mus81 in the regulation of chemosensitivity in HCC still remains unclear." (PMID 26714930, 2016).
melanoma (1 paper, 2021). A malignant, usually aggressive tumor composed of atypical, neoplastic melanocytes. "In melanoma brain metastases, heterozygous copy number loss of HR and SSB repair, but no mismatch repair-associated genes, was found, which from the most prevalent genes were APTX, FEN1, GTF2H5, DNA2, MUS81 and TOP3A." (PMID 34885093, 2021).
promyelocytic leukemia (1 paper, 2020). "Physical binding of MUS81 to telomeres, as well as colocalization of MUS81 with telomere-containing promyelocytic leukemia bodies in ALT cells provided evidence of a direct role for MUS81 in human ALT." (PMID 32469862, 2020).
Rothmund-Thomson syndrome (1 paper, 2025). "We also observe that a mutation associated with Rothmund-Thomson syndrome, which produces a truncated RECQ4 unable to interact with MUS81, recapitulates these chromosome instability phenotypes." (PMID 39900600, 2025).
thyroid cancer (1 paper, 2020). "Breast and thyroid cancer tissues from patients with germline MUS81 c.1292G>A (p.R431H) exhibited negative or lower MUS81 expression levels compared with wild-type BC, and normal breast and thyroid tissues." (PMID 32443704, 2020).
thyroid tumor (1 paper, 2020). A benign or malignant neoplasm affecting the thyroid gland. "Of note, normal tissue adjacent to the thyroid tumor positive for c.1292G>A presented scatted cells with low MUS81 cytoplasmic expression, as well as a few normal cells with low nuclear MUS81 expression (data not shown)." (PMID 32443704, 2020).
cancer (34 papers, 2009 to 2026). A tumor composed of atypical neoplastic, often pleomorphic cells that invade other tissues. "Dual loss of BRCA2 and MUS81 results in obvious cancer cell death, indicating a pivotal role of MUS81 in BRCA2-mutated cancer cells." (PMID 33791310, 2021). "Nevertheless, in WRN-depleted microsatellite instability (MSI) cancer cells, MUS81 complex shatters chromosomes, which causes apoptosis of cancer cells." (PMID 33791310, 2021). "Herein, this review focuses on recent understanding of how MUS81 works in distinct cancer cells and discuss why MUS81 causes such different consequences as black and white in tumors." (PMID 33791310, 2021). "Surprisingly, BRCA1, RAD51, or RAD51C depletion, unlike BRCA2 depletion, cannot lead to synthetic lethality upon concomitant loss of MUS81 in cancer cells." (PMID 33791310, 2021). "Nonetheless, a growing number of evidence prove that MUS81 plays a dominant role in some specific gene-mutated cancer cells." (PMID 33791310, 2021). "Four of five patients positive for MUS81 c.1292G>A had at least one other variant in a cancer-related gene." (PMID 32443704, 2020). "We constructed a protein–protein interaction (PPI) network with MUS81 and 17 cancer-related genes detected with a variant in our exome analysis, to identify biological relationships among them." (PMID 32443704, 2020). "Using the whole-exome sequencing approach, we were able to identify pathogenic and likely pathogenic variants in cancer-related genes and a novel variant mapped to the DNA repair gene MUS81 associated with familial TC and BC cases." (PMID 32443704, 2020). "MUS81 provides a mechanism for replication stress tolerance, which can be exploited therapeutically, for the reason that the dysregulated division of cancer cells causes DNA damage." (PMID 31803609, 2019). "The correct function of Mus81-Eme1/Mms4 is necessary to prevent genomic instability, a hallmark of cancer." (PMID 23901010, 2013). "As defects in DNA damage repair are frequently interrelated with high predisposition to cancer, research has been carried out to demonstrate whether MUS81 suppresses tumors in vivo." (PMID 33791310, 2021). "However, an intricate picture has emerged from studies in which discrepant gene mutations completely alter the role of MUS81 in human cancers." (PMID 33791310, 2021). "Future studies would help to clarify whether these variants are associated with BC and TC and/or interact with MUS81, contributing to the cancer phenotype." (PMID 32443704, 2020). "Although it is unclear whether Mus81 is important to avoid tumorigenesis, Mus81-associated defects have been linked to some types of cancers, and this endonuclease has been involved in oncogene-induced genotoxicity." (PMID 23901010, 2013). "We identified variants in cancer-related genes that could potentially play a role in familial BC and TC, as well as MUS81 c.1292G>A penetrance moderator in three patients (M1, M3, and M4) that had both the MUS81 c.1292G>A and an additional variant in a cancer-related gene." (PMID 32443704, 2020). "These inhibitors can also serve as chemical biology tools for a deeper study of MUS81 function and as leads for drug discovery aimed at therapies exploiting DNA repair vulnerabilities in cancer treatment." (PMID 41740057, 2026). "Both compounds effectively inhibit MUS81 in vitro and in cells, sensitizing cancer cells to DNA-damaging agents by impairing DNA repair." (PMID 41740057, 2026). "MUS81 has been investigated as a potential cancer therapeutic target, in part because MUS81 defects sensitize cells to genotoxic agents." (PMID 38069223, 2023). "MUS81 expressions in cancer cell LNCaP, PC3, and DU145 were higher than those in healthy human prostate epithelial cell line RWPE-1, and its expression in LNCaP cells was higher than that in PC3 and DU145 cells." (PMID 35910852, 2022).
cancer (continued). "Despite such research indicating differential expression of MUS81 in different human tissues and potential roles in malignant tumors, its expressions and roles in CRPC remain to be determined." (PMID 35910852, 2022). "Here, we review the recent understanding of how MUS81 functions in tumors with distinct genetic backgrounds and discuss the potential therapeutic strategies targeting MUS81 in cancer." (PMID 33791310, 2021). "It would be interesting to uncover the mechanism by which MUS81 insufficiency leads to such different phenotypes between BRCA1- and BRCA2-deficient cancer cells." (PMID 33791310, 2021). "Inhibitions of MUS81 improve the chemical sensitivity of various anti-cancer drugs, such as 5-fluorouracil, camptothecin, olaparib and cisplatin by different mechanisms in diverse cancer cells." (PMID 34527278, 2021). "In recent findings, it is becoming increasingly evident that MUS81 has close relationships with cancers." (PMID 33791310, 2021). "This need for better understanding especially in the context of current combinatorial cancer therapy is highlighted by the fact that BRCA2-deficient tumors under dual PARP inhibition and MUS81 depletion have improved viability compared to either alone." (PMID 33043007, 2020). "In hepatocellular and BC cells, depletion of MUS81 increased chemosensitivity, highlighting a potential target for cancer treatment." (PMID 32443704, 2020). "Our data uncovered that downregulation of MUS81 brought a higher sensitivity to the chemotherapy drugs CPT and Olaparib; therefore, we proposed a novel anti-cancer strategy that involves inhibiting MUS81." (PMID 31803609, 2019). "Of note, recent studies have discovered that MUS81 expression levels correlate well with the evolution of various cancers such as colorectal carcinoma and lung cancer." (PMID 31803609, 2019). "Previous evidence has indicated that MUS81 activity was required for cell survival under DNA damage, such as endogenous agents or anti-cancer compounds." (PMID 31803609, 2019). "Thus, by allowing a small window towards mutagenesis and genome rearrangements, which in long term could be advantageous to both cancer cells and evolution, the Cdk1/Cdc5/Mus81-Mms4 pathway protects against more severe loss of information, which in short term would endanger cellular life." (PMID 23531881, 2013). "These genes are involved in the regulation of cell cycle (CCND1, CDCA5, FOSL1, KDM2A, NUMA1, RHOD), apoptosis (FADD, ORAOV1), or the DNA damage response (DDB1, KAT/TIP60, MUS81, PACS1, RPS3), and several have been implicated in the HPV lifecycle and/or HPV-associated cancers." (PMID 40892869, 2025). "Therefore, when WRN is inactivated, the “genomic scar” will be cleaved by MUS81 endonuclease, resulting in cancer cell death." (PMID 39759116, 2025). "Based on the gene set enrichment analysis in malignant tumors, MUS81 may play a critical role in many signaling pathways, such as the cell cycle regulation and DNA damage response pathways." (PMID 35480096, 2022). "MUS81 is a DNA repair factor reported to be a source of cytoplasmic DNA in cancer cells." (PMID 35634291, 2022). "The roles of MUS81 in cancer depend on the tumor genetic background." (PMID 36203968, 2022). "MUS81 might act as a tumor suppressor in cancers with low expression levels and as an oncogene-like molecule in those tumors with high MUS81 expression levels." (PMID 34625086, 2021). "Accordingly, MUS81 inhibitors that specifically bind to MUS81 might enhance the chemosensitivity in the cancer cells leading to improving the efficiency of therapeutic treatment." (PMID 34527278, 2021). "Furthermore, multi-immunofluorescence staining analysis indicated that compared with monotherapy or parental groups, the combination therapy remarkably increased CD8+ T cell infiltration and perforin in MUS81 knockdown cancer cells." (PMID 34625086, 2021).